CHST14 (carbohydrate sulfotransferase 14)
Description:
Catalyzes the transfer of sulfate to position 4 of the N-acetylgalactosamine (GalNAc) residue of dermatan sulfate. Plays a pivotal role in the formation of 4-0-sulfated IdoA blocks in dermatan sulfate. Transfers sulfate to the C-4 hydroxyl of beta1,4-linked GalNAc that is substituted with an alpha-linked iduronic acid (IdoUA) at the C-3 hydroxyl. Transfers sulfate more efficiently to GalNAc residues in -IdoUA-GalNAc-IdoUA-than in -GlcUA-GalNAc-GlcUA-sequences. Has preference for partially desulfated dermatan sulfate. Addition of sulfate to GalNAc may occur immediately after epimerization of GlcUA to IdoUA. Appears to have an important role in the formation of the cerebellar neural network during postnatal brain development.
Synonyms: D4ST-1; D4ST1; HD4ST; ATCS; EDSMC1; HNK1ST
Tractability: Antibody: UniProt predicts a signal peptide or a membrane-spanning region. PROTAC: ubiquitination databases record sites on it; its protein half-life has been measured.
Gene: Protein-coding gene on chromosome 15 (40,470,984 to 40,473,158, forward strand). Ensembl gene ENSG00000169105.
Subcellular location: Golgi apparatus membrane
Subcellular location (Human Protein Atlas): Golgi apparatus
Pathways (Reactome):
Disease: Defective CHST14 causes EDS, musculocontractural type
Metabolism: DS-GAG biosynthesis
Gene Ontology:
Molecular function: dermatan 4-sulfotransferase activity; protein binding; phosphate ion binding; sulfotransferase activity
Biological process: dermatan sulfate proteoglycan biosynthetic process; dermatan sulfate proteoglycan metabolic process; carbohydrate biosynthetic process; glycoprotein biosynthetic process
Cellular component: extracellular exosome; Golgi membrane; membrane; Golgi apparatus
Genetic constraint (gnomAD): Loss-of-function variants: 13 observed, 22.55 expected, observed/expected ratio (o/e) 0.58, 90% interval 0.37 to 0.92. The upper end of that interval is the gene's LOEUF score, 0.92, which puts it in group 3 of 6, group 1 being the genes least tolerant of losing a copy. Missense variants: 466 observed, 491.15 expected, observed/expected ratio (o/e) 0.95, 90% interval 0.88 to 1.02. Synonymous variants: 233 observed, 212.46 expected, observed/expected ratio (o/e) 1.1, 90% interval 0.99 to 1.22.
Gene-disease validity (ClinGen):
ClinGen rates the evidence that CHST14 causes each of these diseases.
Ehlers-Danlos syndrome, musculocontractural type 1 (autosomal recessive): Definitive.
Homologues: Orthologues: macaque CHST14 (98% identical), mouse Chst14 (93% identical), pig CHST14 (88% identical), rat Chst14 (86% identical), guinea pig CHST14 (84% identical), rabbit CHST14 (69% identical), tropical clawed frog chst14 (64% identical), zebrafish chst14 (58% identical). Paralogues in human: CHST13 (31% identical), CHST8 (31% identical), CHST11 (30% identical), CHST12 (28% identical), CHST9 (28% identical), CHST10 (22% identical).
Diseases named in the same sentence as CHST14 in open-access papers:
CHST14 is named in the same sentence as 21 diseases in open-access papers, as found by Europe PMC text mining. Sharing a sentence is not in itself a finding about the gene and the disease. The quoted sentences say what the papers report.
adducted thumb-clubfoot syndrome (12 papers, 2013 to 2026). "Musculocontractural Ehlers-Danlos syndrome (mcEDS) caused by pathogenic variants in the gene that encodes carbohydrate sulfotransferase 14 (CHST14) (mcEDS-CHST14) is a representative disorder of DS deficiency." (PMID 42139064, 2026). "Musculocontractural EDS (mcEDS) is an extremely rare form, with the causative genes recently identified as carbohydrate sulfotransferase 14 (CHST14) or dermatan sulfate epimerase (DSE)." (PMID 39268284, 2024). "Musculocontractural EDS (mcEDS) is a rare subtype of EDS caused by mutations in the genes encoding carbohydrate sulfotransferase 14 (mcEDS-CHST14; MIM#601776) or dermatan sulfate epimerase (mcEDS-DSE; MIM#615539)." (PMID 36833362, 2023). "Musculocontractural EDS (mcEDS) is caused by pathogenic variants in the CHST14 or DSE genes, and spondylodysplastic EDS (spEDS) is caused by pathogenic variants in the B4GALT7 or B3GALT6 genes." (PMID 36101818, 2022).
Ehlers-Danlos syndrome (11 papers, 2015 to 2026). The Ehlers–Danlos syndromes (EDS) are a clinically and genetically heterogeneous group of heritable connective tissue disorders (HCTDs) characterized by joint hypermobility, skin hyperextensibility, and tissue fragility. "We report a 26-year-old male with a genetically confirmed diagnosis of musculocontractural Ehlers-Danlos syndrome (mcEDS), also referred to as autosomal recessive CHST14 deficiency (ICD-10: Q79.6, ORPHA:2953)." (PMID 40760347, 2026). "Gene mutation analysis of CHST3, CHST6 and CHST14 should be performed whenever there is suspicion of spondyloepiphyseal dysplasia, Ehlers-Danlos syndrome, macular corneal dystrophy and ARMJD, respectively." (PMID 37545696, 2023). "Musculocontractural Ehlers-Danlos syndrome (mcEDS) is caused by generalized depletion of dermatan sulfate (DS) due to biallelic pathogenic variants in CHST14 encoding dermatan 4-O-sulfotransferase 1 (D4ST1) (mcEDS-CHST14)." (PMID 34850861, 2021). "Our PPI network analysis also revealed interactions between ZNF469 and CCT candidate genes, including COL5A1, COL1A1, and other genes that regulate eyeball development, such as VSX1 (causing KC and corneal dystrophy) and CHST14 (Ehlers-Danlos Syndrome candidate gene)." (PMID 40547359, 2025). "Musculocontractural Ehlers-Danlos syndrome (mcEDS) is an extremely rare subtype of EDS, caused by pathogenic variants in CHST14 or DSE (dermatan sulfate epimerase, encoded by the DSE gene), leading to severe connective tissue fragility." (PMID 40760347, 2026). "Musculocontractural Ehlers-Danlos syndrome (mcEDS) is a subtype of EDS caused by mutations in the gene for carbohydrate sulfotransferase 14 (CHST14) (mcEDS-CHST14) or dermatan sulfate epimerase (DSE) (mcEDS-DSE)." (PMID 36833362, 2023). "Suspected atypical Ehlers Danlos syndrome (EDS) was later confirmed with the homozygous pathogenic variant NM_130468.4:c.145delG, p.(Val49Ter) in the CHST14 gene (coding for the carbohydrate sulfotransferase 14)." (PMID 41399760, 2026). "In patients with Ehlers-Danlos syndrome who lack Carbohydrate Sulfotransferase 14 (Chst14), this DS chain is substituted with CS." (PMID 39170918, 2024). "Different homozygous mutations in human CHST14 and DSE have been linked to Ehlers-Danlos syndrome (EDS), where patients display, among other symptoms, distinctive craniofacial dysmorphism." (PMID 25793894, 2015).
gastric cancer (2 papers, 2021 to 2022). A primary or metastatic malignant neoplasm involving the stomach. "Furthermore, we identified CHST14 as a potential metabolic target for the EMT subtype for stomach cancer associated with reprogramming of energy metabolism." (PMID 33917859, 2021). "Stomach cancer showed elevated energy metabolism and was associated with an unfavorable prognosis (p < 0.0068) coupled with high expression of CHST14, indicating that it may serve as a potential drug target." (PMID 33917859, 2021). "We found that sulfotransferase activity in the glycan pathway was associated with poor prognosis; however, in our previous pan-cancer analysis, CHST14 was shown to be highly expressed in high-energy-metabolism TCGA gastric cancers with high EMT." (PMID 35326589, 2022). "Thus, considering CHST14 as a legitimate target, we identified candidate drugs (YM155, BEZ235, and SN-38) against CHST14 for stomach cancer." (PMID 33917859, 2021).
colitis (1 paper, 2025). Inflammation of the colon. "Unexpectedly, no significant aggravation of dextran sulfate sodium-induced colitis was observed in Chst14-/- mice compared with wild-type mice." (PMID 40327642, 2025).
colon cancer (1 paper, 2020). "Overexpression of CHST3 and CHST11 have been linked to BC aggressiveness, relapse, and development of metastasis; in contrast, downregulation of CHST10 and CHST14 has been linked to invasive melanoma and to late stages of colon cancer progression, respectively." (PMID 32605588, 2020).
Kyphoscoliosis (1 paper, 2025). An abnormal curvature of the spine in both a coronal (lateral) and sagittal (back-to-front) plane. "The musculocontractural Ehlers–Danlos syndrome (mcEDS), which is characterized by kyphoscoliosis, muscular hypotonia, skin hyperextensibility and fragility, joint hypermobility, and multiple joint dislocations, is caused by DSE or CHST14 mutations." (PMID 40141107, 2025).
memory impairment (1 paper, 2023). "Knockdown mice for the CHST14 gene were linked to spatial learning and memory impairment with the gene action located in the hippocampus." (PMID 36658485, 2023).
motor developmental delay (1 paper, 2023). "Patients with mcEDS-DSE, mcEDS-CHST14, and Chst14-/- mice showed various common symptoms, such as growth impairment, skin fragility, spinal and talipes deformities, hypotonia, and motor developmental delay." (PMID 36833362, 2023). "Patients with mcEDS and Chst14-/- mice showed hypotonia and motor developmental delay." (PMID 36833362, 2023).
prostate carcinoma (1 paper, 2022). A carcinoma that arises from epithelial cells of the prostate gland. "CHST12, CHST13, and CHST14 can also mediate C4S sulfations under some circumstances, however, these enzymes did not respond to castration in the prostate cancer progression PDX model." (PMID 35963852, 2022).
cancer (4 papers, 2010 to 2024). A tumor composed of atypical neoplastic, often pleomorphic cells that invade other tissues. "Our previous study on pan-cancer analysis showed that, when integrated energy metabolism levels are high in a high EMT state, the CHST14 gene is significantly overexpressed." (PMID 35326589, 2022).
connective tissue disorder (4 papers, 2013 to 2023). A disease involving the connective tissue. "Other differential diagnoses for BCS include the musculocontractural form of EDS, another autosomal recessive connective tissue disorder (OMIM: 601776), due to biallelic mutations in CHST14." (PMID 23642083, 2013).
myopathy (4 papers, 2021 to 2023). A disease of the muscle in which the muscle fibers do not function properly. "In pathological analysis, Chst14 deficiency induced myopathy phenotypes, including a predominance of small muscle fiber sizes and type I muscle (slow muscle) fibers, compared with Chst14+/+ and Chst14+/- mice." (PMID 36833362, 2023). "Mutations in Chst14 induced myopathy-related phenotypes and thoracic kyphosis." (PMID 36833362, 2023). "Considering these results, the myopathy phenotype in Chst14−/− and mcEDS may be caused by connective tissue fragility in the skeletal muscle associated with ECM functional changes, including changes in decorin localization and pathological activation." (PMID 34850861, 2021). "These two Chst14−/− mutant mice demonstrated a common pathological phenotype, sharing typical features of the mcEDS phenotype, including loss of DS disaccharides, growth delay, skin fragility, myopathy, reduced muscle function and thoracic kyphosis." (PMID 34850861, 2021). "We identified myopathy phenotypes in Chst14-deficient mice using an mcEDS model." (PMID 34708033, 2021). "We developed CRISPR/Cas9-genome engineered Chst14 mutant (Chst14–/–) mice, which showed a pathological phenotype and shared the typical mcEDS phenotype features, including loss of DS, growth delay, skin fragility, myopathy, reduced muscle function, and thoracic kyphosis." (PMID 34708033, 2021). "Chst14–/– mice had small muscle fibers within the spread interstitium; however, histopathological findings indicated milder myopathy in Chst14–/– mice." (PMID 34708033, 2021). "We also identified several myopathy phenotypes in Chst14−/− mice, including a predominance of small muscle fiber size and type I muscle fibers, both of which are characteristic phenotypes found in patients with mcEDS." (PMID 34850861, 2021). "Therefore, the loose meshwork of fibers might be associated with the myopathy phenotype in Chst14–/– mice, and mcEDS may be caused by connective tissue fragility in the skeletal muscle, associated with ECM functional changes including ectopic localization of decorin." (PMID 34708033, 2021). "In the present study, we investigated the effects of decorin on spatial distribution and expression in myopathy using Chst14–/– mice as an mcEDS model." (PMID 34708033, 2021). "The functional alteration by decorin-proteoglycan in Chst14–/– mice might lead the myopathy phenotype in the muscle." (PMID 34708033, 2021). "Although dystrophic muscles showed a larger number of smaller fibers, occurrence of hypertrophic fibers, and high levels of creatine kinase, a marker of muscle damage, this was not confirmed in Chst14–/– mice, suggesting milder phenotypes of myopathy in mcEDS." (PMID 34708033, 2021).
CHST14 also shares sentences with these, for which no sentence is quoted: macular corneal dystrophy (2 papers); colorectal cancer (1); corneal dystrophy (1); laryngeal carcinoma (1); melanoma (1); neurodevelopmental disorder (1); periodontitis (1); spondyloepiphyseal dysplasia (1); stomach cancer (1).